TEX28P2 (TEX28 pseudogene 2)
Synonyms: pTEX; CXorf2B
Gene: Transcribed unprocessed pseudogene on chromosome X (154,159,357 to 154,176,349, reverse strand). Ensembl gene ENSG00000277008.
Subcellular location: Membrane